ALB (albumin)
Diseases named in the same sentence as ALB in open-access papers (continued):
Sharing a sentence is not in itself a finding about the gene and the disease.
liver disease (continued). "The correct subphenotyping can guide clinical management using fluid resuscitation (albumin) alone for hypovolemia, or addition of vasopressor therapy (e.g., terlipressin) for fluid-refractory hepatorenal syndrome, versus supportive care and additional diagnostic testing for intrinsic AKI." (PMID 40802457, 2025). "Compared to earlier stages of liver disease, other factors could be of higher relevance for its pathogenesis, i.e. albumin, which we found to be significantly associated with post-TIPS oHE in all employed statistical models." (PMID 39656322, 2024). "We showed that the best predictor of HCC incidence after SVR was given by the association of two easy and accurate markers, undoubtedly associated with portal hypertension and liver function: platelet count and albumin level, analyzed prospectively at long-term FU after SVR." (PMID 38793565, 2024). "As heart failure progresses, people withheart failure often have other chronic conditions, such as chronic kidney diseaseand liver disease, that may result in reduced albumin synthesis or increased loss." (PMID 39742221, 2024). "Other possible causes of low albumin are liver disease or kidney disease." (PMID 38644839, 2024). "Estimation of albumin gradient in peritoneal effusion is based on the determination of albumin in ascites and serum to determine whether ascites is caused by portal hypertension." (PMID 37359904, 2023). "SMT differed between studies and included, among other things, the use of diuretics, lactulose for hepatic encephalopathy, albumin administration, antibiotics for symptoms of infection, and antiviral drugs when the underlying liver disease was of viral etiology." (PMID 37892679, 2023). "Taken together, findings from these acute and chronic alcohol exposure studies were consistent with our results, suggesting that reduced albumin levels could be a risk factor for cardiovascular diseases, liver diseases, and kidney diseases." (PMID 36290642, 2022). "Additionally, decreased protein and albumin, such as hers, can be found in cases of nephrotic syndrome but also in cases of hepatic disease, causing increased capillary permeability and decreased albumin synthesis." (PMID 36049202, 2022). "Before PSM, the RFA group had significantly less para-vessel lesions than the MWA group (44.1% vs. 19.2%) but were associated with worse underlying liver disease such as lower prothrombin time, and albumin and platelet counts (86.8 vs. 77.3%, 3.9 vs. 3.7 g/dl, 14.2 vs. 11.8 × 104/μl, respectively)." (PMID 33675382, 2021). "In addition to frailty severity, other variables including: patient age, comorbid liver disease, high serum phosphate, and low serum albumin were also predictive of an increased risk for cumulative time admitted to hospital." (PMID 34178362, 2021). "In our study, the decompensated cirrhotic patients with E/e′ ratio ≥ 10 had significantly higher Child-Pugh score, MELD score, and lower serum albumin as compared to patients with E/e′ ratio < 10.This association of E/e′ ratio with the severity of liver disease is also found in previous studies." (PMID 34900353, 2021). "Further deterioration of zinc transport and distribution by albumin may be caused by glycation, another common molecular alteration encountered in liver disease." (PMID 34836265, 2021). "For patients with an underlying liver disease albumin is even bifunctional and does not only cover the patient’s nutritive status: As albumin is an important indicator of the remnant liver function this even enhances the role of this parameter for the PNI and its predictive ability." (PMID 34439116, 2021). "Distinct plasma-mediated inflammatory responses, as defined by our laboratory assay and changes in WCC and CRP from baseline during the first week of hospitalization, were associated with organ dysfunction and death in albumin-treated advanced liver disease patients." (PMID 31446184, 2020).
liver disease (continued). "Furthermore, although it is not a specific marker of protein malnutrition because its serum concentration is affected by factors such as kidney and liver disease, iron deficiency, and cancer, this protein responds faster to nutritional therapy than albumin." (PMID 28866982, 2017). "Also weight loss or low serum albumin levels of liver disease would be contributed to the complications." (PMID 27259513, 2016). "Similar criteria were associated with a higher risk on an SAE: a history of decompensated liver disease (RR 1.81), platelet count (RR 1.45), albumin (RR 2.03), bilirubin (RR1.89), hemoglobin (RR 1.72), malignancy (RR 2.31) and presence of cardiac disease (RR 1.97)." (PMID 27598789, 2016). "In contrast, fructosamine measurements may be altered in conditions associated with low concentrations of albumin and plasma proteins such as nephrotic syndrome or liver disease particularly cirrhosis which is common among PLWH." (PMID 26273478, 2015). "As an example, a 60-year-old man living in a deprived area, who is alcohol dependent but not a methadone user, with transaminase=70 U/L, ALP=130 U/L, GGT=45 U/L and albumin=38, has a score of 29, which corresponds to a liver disease risk within 2 years of 4.1%." (PMID 24889852, 2014). "Increased total protein levels can be associated with liver disease but often remain in the normal range (4.6–6.9 g/dL), typically due to a decrease in plasma albumin concentration and a concomitant increase of plasma globulin levels, including ALT, AST, and ALP." (PMID 22609946, 2012). "More over lower serum albumin and progressive liver disease was also associated with the coexistence of mutant variant of viruses that might have higher pathogenecity and replication ability." (PMID 19775459, 2009). "Hyperoncotic albumin may be of particular clinical value in edematous states such as those encountered in liver disease, high-risk neonates, brain injury and nephrotic syndrome." (PMID 18318896, 2008). "Furthermore, albumin and thrombin time are closely associated with liver disease severity and in the multivariate analysis of the study for OS, liver cirrhosis was almost statistically significant (p=0.06) suggesting possible significant values with greater samples." (PMID 40948746, 2025). "Furthermore, IL-6 is positively associated with total bilirubin and INR while being negatively associated with serum albumin and platelets, implying that IL-6 might potentially be used as a marker for the progression of liver disease." (PMID 39071840, 2024). "The model for end-stage liver disease score was associated with the development of major complications, whereas cACLD presence, thrombocytopenia, portal hypertension (PH), Child-Pugh score and Albumin-Bilirubin score were found to be predictors of clinically significative PHLF." (PMID 35454842, 2022). "Serum albumin level could be low despite a normal nutritional status due to dilution caused by hypervolemia and conditions with decreased albumin synthesis such as liver disease." (PMID 34079810, 2021). "Portal hypertension (PH) causes severe complications in patients with liver cirrhosis, such as variceal bleeding and ascites; however, data on the knowledge and perceptions on guideline recommendations for the management of varices and the use of albumin is scarce." (PMID 33270161, 2021). "On the other hand, ascites noticed in dogs with chronic hepatitis may be related to intrahepatic portal hypertension and diminished albumin assembly, weight loss may be attributed to anorexia and catabolic state, and melena may be as a result of coagulopathies." (PMID 29915506, 2018). "Albumin therapy in liver disease patients might therefore be associated with risk of hemorrhage." (PMID 28800610, 2017). "Patients with CS exhibited more frequent portal hypertension, lower platelet counts, higher bilirubin and international normalized ratio levels, and lower serum albumin compared with patients with CD." (PMID 41888235, 2026).
liver disease (continued). "Oxidized albumin is a predictor for mortality in liver disease, but little is known about oxidized albumin in other diseases." (PMID 41770297, 2026). "While albumin levels typically decrease due to impaired synthesis in liver disease, PCHE levels decrease due to both impaired synthesis and reduced enzymatic activity." (PMID 41493845, 2026). "Urinary ascites is a rare cause of ascites that can present with a high serum-ascites albumin gradient (SAAG), mimicking portal hypertension." (PMID 41835653, 2026). "Post-translational modifications of human serum albumin (HSA) have been described in patients with liver disease." (PMID 41683923, 2026). "Supportive care included fluid management, albumin infusions, and diuresis, but hepatorenal syndrome developed, requiring continuous renal replacement therapy (CRRT)." (PMID 40190874, 2025). "Albumin, a liver-produced plasma protein with anti-inflammatory and antioxidant properties, is reduced in advanced liver disease." (PMID 40806286, 2025). "Factors that affect liver function, such as liver disease or nutritional status, can influence albumin synthesis and, consequently, serum albumin levels." (PMID 40699702, 2025). "In liver disease patients, hepatic dysfunction directly compromises albumin synthesis, which is a core component of PNI calculation." (PMID 40727696, 2025). "CRP is a key marker of inflammation, while the albumin level decreases not only in inflammatory conditions but also due to factors such as liver diseases, kidney diseases, and malnutrition." (PMID 40087374, 2025). "This study used an albumin-deficientmouse model to investigate the relevance of albumin in PFOS tissuedistribution and liver disease end points." (PMID 40492927, 2025). "The same is true for albumin, which is only partially affected by nutritional status, with some diseases having a greater impact on albumin levels (e.g., liver disease, infections)." (PMID 40415246, 2025). "As expected, we observed elevated serum levels of bilirubin, internalized normalized ratio (INR) and decreased albumin values in more severe liver disease." (PMID 41028194, 2025). "Several studies have demonstrated that an elevated hepatic venous pressure gradient correlates with SI severity and low albumin level in patients with portal hypertension." (PMID 40747208, 2025). "A new model was developed based on heart rate, blood pressure, hemoglobin, history of peptic ulcer, comorbid liver disease, albumin, platelet count, and CRP." (PMID 41585275, 2025). "This is not represented in clinical guidance in the UK, although the link between albumin and liver disease is well known." (PMID 40941010, 2025). "Older age, metabolic dysfunction-associated steatotic liver disease, previous treatment with lactulose, ACLF, white blood cell counts or albumin levels at admission were associated with OHE (P < 0.05)." (PMID 41439114, 2025). "Consistency of these outcomes across multiple studies highlighted the necessity to address albumin’s dual role, both as a plasma expander and as a modulator of broader physiological processes in patients with advanced liver disease." (PMID 40662011, 2025). "Liver Disease: In liver failure, serum albumin levels are often reduced, and the fraction of structurally modified albumin (e.g., oxidized or nitrosylated) increases." (PMID 40801572, 2025). "The CP score is used to assess the severity of liver disease on the basis of the degree of hepatic encephalopathy, the degree of ascites, serum albumin and bilirubin levels, and prothrombin prolongation time." (PMID 41573251, 2025). "This process selected eight predictors: heart rate, systolic blood pressure, hemoglobin, history of peptic ulcer, history of liver disease, platelet count, albumin, and CRP." (PMID 41585275, 2025). "The patient was a 52-year-old female alcoholic suffering from severe liver disease and had albumin of 4 g/dL on admission that dropped to 2.7 while hospitalized." (PMID 40051558, 2025).
liver disease (continued). "Our findings suggest that the increase in the free fraction of TEIC due to decreased ALB is a key driving factor in patients with liver disease, further supporting the model’s ability to capture pathophysiological mechanisms." (PMID 41424785, 2025). "Low serum albumin concentrations as a result of liver disease indicated diffuse and chronic hepatopathies." (PMID 40271488, 2025). "Significant differences in LMR, PNR, and neutrophil–lymphocyte–albumin ratio further support their potential as inflammatory markers in advanced liver disease." (PMID 40364106, 2025). "Currently, albumin infusion is recommended in specific clinical situations, such as spontaneous bacterial peritonitis, hepatorenal syndrome, and large-volume paracentesis in liver cirrhosis." (PMID 40649163, 2025). "Following the MWA procedure, there was a notable rise in the levels of alanine transaminase, aspartate transaminase, total bilirubin, prothrombin time, and the Child–Pugh, albumin–bilirubin, and model for end‐stage liver disease scores (p < 0.05)." (PMID 41245224, 2025). "In HCC patients’ liver function is often impaired due to an associated underlying liver disease (e.g. hepatitis, nonalcoholic fatty liver disease) and CRP and albumin are primarily synthesized by hepatocytes." (PMID 41142780, 2025). "The serum-ascites albumin gradient (SAAG) was calculated at 1.8 g/dL (serum albumin: 3.0 g/dL; ascitic fluid albumin: 1.2 g/dL), consistent with a diagnosis of portal hypertension-related ascites." (PMID 40762000, 2025). "These patients were significantly older, showed higher levels of quantitative HDV RNA and more advanced liver disease as reflected by lower levels of platelets and albumin and higher INR." (PMID 39846714, 2025). "Its unique strength lies in using only two objective laboratory parameters—albumin and bilirubin—which are central to the pathophysiology of liver disease." (PMID 40604547, 2025). "The data were used, in combination with demographic and serum albumin changes, to generate a cholestatic liver disease pharmacokinetic model." (PMID 41240411, 2025). "PA is a transport protein synthesized by hepatocytes; it is more sensitive than albumin due to its short half-life, rapid renewal, and minimal influence on liver disease and blood product transfusions." (PMID 40017523, 2025). "The subgroup of patients with liver cirrhosis and the development of the primary endpoint were significantly older and had more advanced liver disease as reflected by significantly lower platelet and albumin levels and higher levels of bilirubin." (PMID 39846714, 2025). "Low albumin concentrations can signal poor nutrition, liver disease, sepsis, or nephrotic syndrome, and have also been associated with an elevated risk of cancer in various populations." (PMID 40941010, 2025). "The albumin–bilirubin (ALBI) score is a contemporary parameter calculated using serum albumin and plasma total bilirubin levels, initially utilized to assess the hepatic reserve capacity in patients with liver disease." (PMID 40364067, 2025). "Cases had significantly higher bilirubin, lower albumin, and platelet levels, all consistent with more advanced liver disease." (PMID 40080923, 2025). "In the preliminary phase, various molar ratios (ligands/albumin) were tested on patients with liver diseases and control patients." (PMID 38228668, 2024). "The combination of plasma exchange (PE) and plasma perfusion (PP) in patients with liver disease enables the efficient removal of a significant quantity of toxic substances, as well as the improvement of clotting factors and albumin levels." (PMID 39493711, 2024). "A decrease in the serum-pleural effusion albumin gap of less than 11 g/L after TIPS was another indication of an etiology other than portal hypertension." (PMID 39109224, 2024). "Less advanced liver disease in the refugee population also explains the significant differences in laboratory parameters, such as albumin and bilirubin levels." (PMID 39768565, 2024).
liver disease (continued). "Measuring total protein levels and albumin-to-globulin ratios can aid in detecting various health issues, including liver disease." (PMID 38765133, 2024). "This increases blood flow through the portal system, aggravating the course of portal hypertension and increasing the severity of ascites, into which albumin and sodium are lost." (PMID 38337613, 2024). "The majority of the patients had well-preserved synthetic function (eg, bilirubin and albumin), fewer than 15% had evidence of portal hypertension, and nearly 80% had early-stage HCC (BCLC-0 or BCLC-A)." (PMID 39495142, 2024). "It has been reported that serum albumin levels change in response to the stage of liver disease, and synthesis rates decrease in those with liver disease." (PMID 38826899, 2024). "Investigations revealed a dilated portal vein, esophageal varices, and high serum-albumin gradient ascites, all of which point to a presinusoidal etiology of portal hypertension." (PMID 38562337, 2024). "Together with portal hypertension and low circulating albumin concentrations, the PV increases with the severity of the disease." (PMID 38667480, 2024). "CTP score was initially designed to reflect the severity of liver disease, which not only considers liver function (bilirubin, albumin, prothrombin time) but also incorporates clinical manifestations." (PMID 38658605, 2024). "Terlipressin plus albumin resulted in a significantly higher rate of Hepatorenal syndrome reversal vs. albumin alone in patients with Hepatorenal syndrome type 1." (PMID 39286706, 2024). "ALB can maintain the osmotic pressure–fluid exchange balance; in addition, its serum expression can increase with liver disease severity." (PMID 39625960, 2024). "LPC species levels inversely correlated with the model of end-stage liver disease score and directly with baseline and post-therapy albumin levels." (PMID 38256273, 2024). "Predictors of treatment failure included male sex, treatment duration <8 weeks, treatment discontinuation due to adverse events, advanced liver disease, low albumin, high bilirubin, and substance use." (PMID 39066420, 2024). "This is because albumin has shown to reduce i) the number of liver-disease-related complications and ii) the time spent in hospital." (PMID 38551716, 2024). "Among them, hepatocyte function-related genes, such as ALB and CYP3A4, as liver-disease risk factors, were downregulated in aged liver." (PMID 37378670, 2024). "Inflammatory responses, liver disease, cancer, or idiopathic factors can influence various serum proteins and albumin levels." (PMID 38794723, 2024). "Norepinephrine in combination with albumin is as effective as terlipressin in combination with albumin when used for the management of hepatorenal syndrome (HRS) type 1." (PMID 39286706, 2024). "Albumin kinetics vary among patients and are influenced by factors like hepatic disease, malignancy, kidney disease, and albumin transfusion." (PMID 38576552, 2024). "The treatment of choice for hepatorenal syndrome-acute kidney injury (HRS-AKI) is vasoconstrictor therapy in combination with albumin, preferably norepinephrine or terlipressin as recommended by recent guidelines." (PMID 38285703, 2024). "Thereafter, the clinical relevance of other albumin modifications has been investigated in advanced liver diseases 10,12." (PMID 38228668, 2024). "Patients initiating TNF inhibitors also had a lower prevalence of comorbidities, except liver disease and depression, and had higher white blood cell counts and eGFR levels and lower serum albumin levels." (PMID 38625700, 2024). "Thirdly, studies had shown that compared to hepatitis B, WD cirrhosis presented with less severe portal hypertension, lower prothrombin time and transaminase levels, and higher albumin levels." (PMID 38627672, 2024).